LINGO1 (leucine rich repeat and Ig domain containing 1)
Description:
Functional component of the Nogo receptor signaling complex (RTN4R/NGFR) in RhoA activation responsible for some inhibition of axonal regeneration by myelin-associated factors. Is also an important negative regulator of oligodentrocyte differentiation and axonal myelination. Acts in conjunction with RTN4 and RTN4R in regulating neuronal precursor cell motility during cortical development (By similarity).
Synonyms: LERN1; LRRN6A; FLJ14594; MRT64; UNQ201
Tractability: Antibody: a drug acting on it is in phase 2 or 3 trials; its Gene Ontology location is reachable by antibodies, with high confidence; UniProt places it where antibodies can reach, with medium confidence; UniProt predicts a signal peptide or a membrane-spanning region; the Human Protein Atlas places it where antibodies can reach. PROTAC: its protein half-life has been measured.
Gene: Protein-coding gene on chromosome 15 (77,613,027 to 77,820,900, reverse strand). Ensembl gene ENSG00000169783.
Subcellular location: Cell membrane
Subcellular location (Human Protein Atlas): Plasma membrane
Pathways (Reactome):
Signal Transduction: Axonal growth inhibition (RHOA activation)
Gene Ontology:
Molecular function: protein binding; epidermal growth factor receptor binding; signaling receptor activity
Biological process: neuron development
Cellular component: plasma membrane
Genetic constraint (gnomAD): Loss-of-function variants: 11 observed, 33.12 expected, observed/expected ratio (o/e) 0.33, 90% interval 0.21 to 0.55. The upper end of that interval is the gene's LOEUF score, 0.55, which puts it in group 2 of 6, group 1 being the genes least tolerant of losing a copy. Missense variants: 585 observed, 873.35 expected, observed/expected ratio (o/e) 0.67, 90% interval 0.62 to 0.72. Synonymous variants: 387 observed, 400.87 expected, observed/expected ratio (o/e) 0.97, 90% interval 0.89 to 1.05.
Homologues: Orthologues: chimpanzee LINGO1 (100% identical), guinea pig LINGO1 (99% identical), pig LINGO1 (99% identical), macaque LINGO1 (99% identical), dog LINGO1 (99% identical), mouse Lingo1 (98% identical), rat Lingo1 (98% identical), rabbit LINGO1 (97% identical), tropical clawed frog lingo1 (82% identical), zebrafish lingo1a (81% identical), zebrafish lingo1b (73% identical). Paralogues in human: LINGO2 (59% identical), LRRN1 (25% identical), LRRN2 (23% identical), LRRN3 (23% identical), SLIT1 (23% identical), LRFN5 (21% identical), SLIT2 (21% identical), LRFN4 (21% identical), LRFN3 (21% identical), TLR9 (21% identical), LRFN1 (20% identical), LRFN2 (20% identical), and 13 more.
Diseases named in the same sentence as LINGO1 in open-access papers:
LINGO1 is named in the same sentence as 67 diseases in open-access papers, as found by Europe PMC text mining. Sharing a sentence is not in itself a finding about the gene and the disease. The quoted sentences say what the papers report.
Parkinson disease (15 papers, 2008 to 2025). A progressive degenerative disorder of the central nervous system characterized by loss of dopamine producing neurons in the substantia nigra and the presence of Lewy bodies in the substantia nigra and locus coeruleus. "LINGO1 is critical for CNS development, with variants linked to higher risk and altered phenotypes in essential tremor and Parkinson’s disease." (PMID 41510233, 2025). "Elevated LINGO-1 expression is associated with neural injury and several CNS diseases including spinal cord injury, ischemic strokes, Alzheimer’s disease, Parkinson’s disease, and schizophrenia." (PMID 38985935, 2024). "Indeed, in the brain overexpression of LINGO1 has been implicated in both essential tremor as well as movement disorders such as Parkinson’s disease." (PMID 40752573, 2025). "LINGO1 promotes APP degradation, contributing to Aβ deposition Aβ and its up-regulation is implicated in AD and Parkinson’s disease." (PMID 39868232, 2025). "LINGO1 and LINGO2 are associated with increased risk of essential tremor and Parkinson’s disease, and a single nucleotide polymorphism of LINGO2 is associated with increased risk of AD." (PMID 38918213, 2024). "In a study that used a mouse model of Parkinson's disease, survival of dopaminergic neurons increased and behavioral abnormalities were reduced in LINGO‐1–knockout mice compared to wild‐type mice." (PMID 32562344, 2020). "LINGO‐1 is expressed in neurons and oligodendrocytes of the CNS and is significantly upregulated in various neurological disorders such as Parkinson's disease, multiple sclerosis, and nerve injuries (eg, spinal cord injury)." (PMID 32562344, 2020). "Compared with controls, LINGO1 protein levels were increased in the cerebellar white matter of Parkinson and ET patients – but for the latter, only when the disease duration exceeded 20 years." (PMID 28729930, 2017). "Several investigations demonstrate an involvement of LINGO-1 in neurodegenerative processes including Alzheimer's disease, Parkinson's disease and multiple sclerosis." (PMID 22235341, 2012). "LINGO-1 upregulation has been demonstrated in oligodendrocyte progenitor cells in MS lesions, in dopaminergic neurons in patients with Parkinson's disease and in rat spinal cord after injury." (PMID 22235341, 2012). "The therapeutic potential of blocking LINGO-1 has been explored in other diseases of the CNS such as Parkinson's disease or multiple sclerosis." (PMID 21311749, 2011). "Moreover, LINGO-1 inhibition improves dopaminergic neuron activity in a model of Parkinson’s disease and promotes spinal cord remyelination in an experimental model of autoimmune encephalomyelitis." (PMID 36901909, 2023). "Additionally, a previous study has shown that the expression of LINGO-1 is upregulated in the substantia nigra of Parkinson’s disease patients and in Parkinson’s disease mice models after neurotoxic lesions." (PMID 34569008, 2022). "LINGO1 and LINGO2 are associated with essential tremor and Parkinson’s disease; however, the function of LINGO2 in carcinogenesis is unknown." (PMID 30696080, 2019). "Moreover, it has been shown that neutralization of LINGO-1 has a positive effect of cell survival in animal models of various CNS disorders including spinal cord injury, MS and Parkinson's disease and LINGO-1 inhibitors are currently evaluated as a treatment option for MS." (PMID 22235341, 2012). "Other proteins with leucine-rich repeats like LINGO-1 and LRRK2 have been shown to play a role in structural and functional integrity of neurons involved in Parkinson's disease." (PMID 18445277, 2008).
essential tremor (9 papers, 2013 to 2025). A relatively common disorder characterized by a fairly specific pattern of tremors which are most prominent in the upper extremities and neck, inducing titubations of the head. "As was shown in a previous publication about the role of LINGO1 in essential tremor risk, individual studies of small number of patients gave very contradictory results." (PMID 23574883, 2013). "Two LINGO1 variants designated as rs9652490 and rs11856808 have been claimed to be associated in case–control GWAS with other neurological conditions such as essential tremor and Parkinson’s disease." (PMID 23574883, 2013). "Linkage studies conducted in families with ET have reported mutations in ETM2 (essential tremor monogenetic locus 2) and (fused in sarcoma) FUS, while other studies have linked (leucine-rich repeat and Ig domain containing 1) LINGO1, FUS and teneurin transmembrane protein 4 (TENM4) with ET3." (PMID 29593234, 2018). "This study adds to other published evidence indicating that, to date, the LINGO1 SNPs studied here could be useful risk biomarkers of developing essential tremor, but not other movement disorders." (PMID 23574883, 2013). "Genes such as LINGO1 rs9652490 and STK32B rs10937625 may influence the incidence of essential tremor." (PMID 36258958, 2022). "An essential tremor SNP (rs3794087 of SLC1A2) is associated with a decreased risk of PD in the Eastern Han Chinese population, while rs9652490 (LINGO1) and rs17590046 (PPARGC1A) do not show an association." (PMID 31755235, 2020).
multiple sclerosis (9 papers, 2011 to 2025). A progressive autoimmune disorder affecting the central nervous system resulting in demyelination. "Owing to its prominent role in myelination and myelin-related processes, Lingo1 has been widely studied in the pathology of neurological conditions, such as multiple sclerosis and spinal cord injury." (PMID 39781463, 2025). "On the other hand, we substantiated previously identified proteins relevant to multiple sclerosis, including LINGO1, which is being explored as a potential therapeutic target to improve remyelination." (PMID 38880880, 2024). "Some recent experimental data suggest a possible role of LINGO-1 in the pathogenesis of multiple sclerosis (MS)." (PMID 23574883, 2013). "Our research demonstrates that LINGO-1 antagonism may be an effective approach to the treatment of the cognitive impairment of multiple sclerosis patients." (PMID 26383267, 2015). "Results from both cell culture experiments and animal studies provide evidence that blocking endogenous LINGO-1 by LINGO-1 antagonists or gene knockouts promote oligodendrocytic differentiation, axonal integrity and remyelinisation in experimental models of multiple sclerosis." (PMID 22235341, 2012). "CSF to serum ratios for anti-LINGO-1 mAb BIIB033 measured 2 weeks post dose are 0.032–0.079% in healthy volunteers and 0.03–0.13% in individuals with multiple sclerosis." (PMID 29558954, 2018).
experimental autoimmune encephalomyelitis (5 papers, 2012 to 2025). An autoimmune demyelinating disease of the central nervous system that is produced experimentally in animals by the injection of homogenized brain or spinal cord in Freund's adjuvant. "It has been shown that mice deficient in LINGO-1 or treated with LINGO-1 neutralizing antibodies exhibit increased remyelinisation in experimental autoimmune encephalomyelitis (EAE), a model of immune-mediated demyelinisation." (PMID 22235341, 2012). "Correspondingly, treatment with anti-LINGO-1 antibody resulted in spinal cord remyelination and improved axonal integrity in MOG-induced experimental autoimmune encephalomyelitis and lysolecithin-induced focal spinal cord demyelination in rats." (PMID 26409478, 2016).
demyelinating disease (4 papers, 2012 to 2023). A broad group of disorders that affect the myelin sheaths that cover the neurons. "Inhibiting the actions of Nogo-A or LINGO-1 promotes remyelination both in vitro and in vivo, while Nogo-A or LINGO-1 antagonists have been suggested as promising therapeutic approaches for demyelinating diseases." (PMID 36901909, 2023). "Given that Lingo1 antibodies can promote recovery from demyelinating disease in animal models, trophic factors that might modulate Nogo-A or Lingo1 activities may offer interesting possibilities for brain repair." (PMID 22452968, 2012). "Thus, the LINGO-1 antibody may be an effective drug for ameliorating the cognitive impairment of demyelinating diseases in the CNS." (PMID 26383267, 2015). "All these data propose that a major function of LINGO-1 is to inhibit the differentiation of OPCs, thereby preventing remyelination and that antagonizing the LINGO-1 function represents potential therapeutics for repair in CNS demyelinating diseases." (PMID 36901909, 2023).
depression (4 papers, 2022 to 2023). "Epigenetic changes in LINGO3 have been correlated with depression and a paralog to LINGO3, LINGO1, acts as a negative regulator of a number of processes key to cognitive function." (PMID 36855151, 2023).
glaucoma (4 papers, 2020 to 2023). Increased pressure in the eyeball due to obstruction of the outflow of aqueous humor. "LINGO-1 is implicated in glaucoma, PD, SCI, traumatic brain injury, MS, essential tremor, as well as AD and epilepsy due to its role in the inhibition of axonal outgrowth, neuronal death, oligodendrocyte differentiation, and myelination." (PMID 36901909, 2023). "More specifically, increased LINGO-1 expression is associated with glaucoma, which is characterized by the degeneration of retinal ganglion cells (RGCs) and their axons." (PMID 36901909, 2023). "Our results provide important insight into the mechanism of LINGO‐1–mediated death of RGCs in patients with glaucoma." (PMID 32562344, 2020). "In glaucoma models and human CNS diseases, LINGO-1 expression has been found to be upregulated." (PMID 33796062, 2021). "In addition, LINGO-1 was found to be increased in models of spinal cord injury and glaucoma." (PMID 33796062, 2021). "The LINGO-1 monoclonal antibody, BIIB033, has shown promise as a neuroprotective and neuroregenerative strategy in clinical studies, but continued evaluations are needed to confirm this promising effect in glaucoma patients." (PMID 33796062, 2021).
Alzheimer disease (3 papers, 2012 to 2025). A progressive, neurodegenerative disease characterized by loss of function and death of nerve cells in several areas of the brain leading to loss of cognitive function such as memory and language. "Several studies have shown that LINGO-1, NgR, and p75 expression are increased in spinal cord injury, dementia, Alzheimer's disease, and vascular cognitive impairments." (PMID 40718448, 2025).
Cognitive impairment (3 papers, 2015 to 2025). Abnormal cognition is characterized by deficits in thinking, reasoning, or remembering. "When the expression of Lingo1 was knocked down through the stereotactic injection of an adeno-associated virus expressing a shRNA sequence against Lingo1 into the hippocampus, the cognitive impairment caused by anesthesia surgery was markedly reversed." (PMID 39781463, 2025). "These pathological changes caused by Lingo1 upregulation after anesthesia and surgery ultimately result in cognitive impairment." (PMID 39781463, 2025). "When Lingo1 expression in hippocampal neurons was knocked down by shRNA(Lingo1), cognitive impairment was substantially attenuated." (PMID 39781463, 2025). "Taken together, these data demonstrated that abnormal Lingo1 upregulation in hippocampal neurons plays a crucial role in the occurrence and development of surgery-induced cognitive impairment." (PMID 39781463, 2025). "Our results demonstrate the potential for the LINGO-1 antibody in treatment of the cognitive impairment of MS." (PMID 26383267, 2015). "Therefore, we will continue to explore the key molecular mechanism by which Lingo1 regulates the development of cognitive deficits after anesthesia and surgery." (PMID 39781463, 2025). "Interestingly, we detected significant upregulation of NgR and p75NTR in the hippocampus after unilateral nephrectomy, suggesting that Lingo1 potentially interacts with NgR and p75NTR during surgery-induced cognitive impairment." (PMID 39781463, 2025). "Furthermore, Lingo1 expression in hippocampal neurons was knocked down to pinpoint its potential role in surgery-induced cognitive impairment in aged mice." (PMID 39781463, 2025). "In general, these results suggest that the upregulation of Lingo1 in hippocampal neurons might be closely related to the occurrence and development of surgery-induced cognitive deficits." (PMID 39781463, 2025). "Importantly, the decreases in myelin levels and neuronal apoptosis in the hippocampus were dramatically inhibited when Lingo1 expression was knocked down by shRNA(Lingo1), which significantly attenuated surgery-induced cognitive impairment." (PMID 39781463, 2025). "Interestingly, we found significant upregulation of Lingo1 in the hippocampus of aged mice with cognitive impairment after unilateral nephrectomy." (PMID 39781463, 2025). "Interestingly, administration of anti-LINGO1 antibodies has been shown to decrease amyloid-β deposition and improve cognitive impairment in a transgenic mouse model of AD68." (PMID 39227716, 2024). "It has been well demonstrated that the LINGO-1 antibody promotes remyelination; however, whether the LINGO-1 antibody could effectively restore the cognitive impairment in EAE mice is still unknown." (PMID 26383267, 2015). "One important implication of these observations is that the LINGO-1 antibody could exert a neuroprotective effect that is effective for treating the cognitive impairment of MS." (PMID 26383267, 2015). "Taken together, our research demonstrated that LINGO-1 antagonism may be an effective approach to the treatment of the cognitive impairment of MS patients." (PMID 26383267, 2015). "Our results suggest that demyelination in the PHC and fimbria-fornix might contribute to cognitive deficits and the LINGO-1 antibody could ameliorate these deficits by promoting myelin growth in the PHC." (PMID 26383267, 2015).
demyelination (3 papers, 2012 to 2023). "Another study confirmed that LINGO-1 antagonism is able to promote repair in the EAE model of demyelination through the ability of LINGO-1 antagonists to promote the differentiation of OPCs." (PMID 36901909, 2023). "More specifically, mice treated with LINGO-1-directed siRNA–chitosan nanoparticles performed better remyelination after ethidium bromide-induced demyelination." (PMID 36901909, 2023). "Inhibition of LINGO-1 by using specific antibodies improved remyelination and neurobehavioral deficits in cuprizone-induced demyelination." (PMID 36901909, 2023). "We investigated LINGO-1 antibody effects on remyelination and neurobehavioral deficit using cuprizone-induced demyelination." (PMID 34712419, 2021). "In this study, the LINGO-1 antibody administration effect on remyelination and behavioral change in the Cuprizone model of demyelination was investigated." (PMID 34712419, 2021). "Therefore, our results demonstrate LINGO-1 antibody improved NF200 in the corpus callosum when administrated intra-peritoneal injection for 3 weeks after cuprizone-induced demyelination." (PMID 34712419, 2021). "In our study, we found that the use of the LINGO-1 antibody improved remyelination and behavioral changes in the CPZ model of demyelination in mice." (PMID 34712419, 2021). "In another study, an LINGO-1 antagonist was demonstrated to promote CNS remyelinisation by directly stimulating OPC differentiation in nonimmune, toxin-induced models of demyelination in rats." (PMID 22235341, 2012).
autism (2 papers, 2022). Persistent deficits in social interaction and communication and interaction as well as a markedly restricted repertoire of activity and interest as well as repetitive patterns of behavior. "Compared with the control group, the mRNA levels of synaptic development‐related genes SYN1, SYNPO, and axon development‐related genes Lingo‐1 were significantly increased in the VPA‐induced autism model group (p < 0.01) and improved after AVP treatment (p < 0.01)." (PMID 36239083, 2022).
Ewing sarcoma (2 papers, 2017 to 2019). A small round cell tumor that lacks morphologic, immunohistochemical, and electron microscopic evidence of neuroectodermal differentiation. "A new surface marker called LINGO-1 was recently identified on Ewing tumours as a potential target for antibody-mediated therapies." (PMID 30613826, 2017). "Notably, on this list, we observed both well-established and candidate oncogenes in Ewing sarcoma, with many of which displayed striking Ewing sarcoma-specific expression profiles (e.g. LINGO1, HOOK1, CITED2 and IGF2BP1)." (PMID 30496486, 2019).
Intellectual disability (2 papers, 2021 to 2025). "Mutations of LINGO1 are associated with intellectual disability, microcephaly, speech and motor delay." (PMID 41012410, 2025).